BRCA1 (BRCA1 DNA repair associated)
Diseases named in the same sentence as BRCA1 in open-access papers (continued):
Sharing a sentence is not in itself a finding about the gene and the disease.
breast cancer (continued). "However, the potential of lincRNAs remains relatively underexplored, particularly in the context of BRCA1-mutated breast cancer and other clinicopathological parameters such as receptor status and patient survival." (PMID 39997609, 2025). "Early detection of BRCA1/2 germline mutational status in breast cancer patients, for example, is crucial for identifying patients who could actually benefit from a PARPi therapy (summarized in16)." (PMID 40278800, 2025). "Deficiencies in the DNA damage repair pathway related genes constitute an important factor in the development of breast cancer, with approximately 10% of breast cancer cases being caused by mutations in HR genes, such as BRCA1, BRCA2, PALB2, BRIP1, BARD1, and RAD51C." (PMID 40830526, 2025). "Furthermore, downregulation of EME1 was also observed when SETD1A was depleted from BRCA1-mutated HCC1937 breast cancer cells, or ATM-mutated H1395 lung cancer cells, suggesting that this represents a conserved mechanism in multiple cancer types." (PMID 39994444, 2025). "The principle of synthetic lethality, which refers to the loss of viability resulting from the disruption of two genes, which, individually, do not cause lethality This principle is primarily used to treat advanced ovarian and breast cancers associated with BRCA1 or BRCA2 gene mutations." (PMID 40978031, 2025). "In addition to enabling enhanced surveillance and access to preventive strategies, early awareness of a germline pathogenic variant in BRCA1/2 or PALB2 vastly influences surgical decision making when a patient is diagnosed with breast cancer." (PMID 40275390, 2025). "Loss of heterozygosity in BRCA1 was observed in her right breast cancer." (PMID 40601170, 2025). "In the context of breast cancer, the mutations of BRCA1 and BRCA2 genes could exert an important impact on the ovarian function." (PMID 41153822, 2025). "Although debated, RR-BSO may also reduce breast cancer risk, therefore, it is important to consider RR-BSO when estimating breast cancer risk in BRCA1/2 carriers." (PMID 40974500, 2025). "Additionally, PRS has been shown to result in absolute risk differences for the development of breast cancer in BRCA1/2 PV carriers." (PMID 40296163, 2025). "In men, BRCA2 mutations are more likely to predispose men to breast cancer, whereas in women, BRCA1 mutations may be comparable to BRCA2 mutations in predisposing women to breast cancer." (PMID 41589155, 2025). "In breast cancer with BRCA1/2 mutation, olaparib or talazoparib has significantly prolonged PFS in OLYMPIAD and EMBRACA trials of metastatic setting, respectively, and olaparib has significantly improved invasive disease-free survival and overall survival (OS) in OLYMPIA trial of adjuvant setting." (PMID 40274769, 2025). "Another example is the phase III OlympiA trial, which included patients with HER2-negative early breast cancer with high-risk clinicopathological features and germline BRCA1 or BRCA2 pathogenic mutations who had received local treatment and neoadjuvant or adjuvant chemotherapy." (PMID 41333222, 2025). "Interestingly, limited ROS production can sufficiently reduce DNA damage and delay tumorigenesis in a BRCA1-deficient breast cancer mouse model." (PMID 39857438, 2025). "By accurately stratifying patients’ risk and guiding targeted screening and preventative interventions, development of a novel prediction model for carriage of BRCA1/2 pathogenic variant in patients with breast cancer will contribute to improved management and outcomes of HBOC." (PMID 40530017, 2025). "A case-control study on 129 cases of breast cancer and 271 controls estimated that any use of supplements containing folic acid at 400 mcg a day was associated with a reduced risk of breast cancer among women, especially in carriers of Breast Cancer gene 1 (BRCA1) mutations." (PMID 40362760, 2025). "The tumor phenotype varies in breast cancer patients based on BRCA1 or BRCA2 germline mutations." (PMID 39997609, 2025).
breast cancer (continued). "This may be due to the fact that common biomarkers for breast cancer, such as BRCA1 and BRCA2, have been linked to liver carcinoma as well." (PMID 40004168, 2025). "However, the oncological safety of NSM in carriers of BRCA1/2 pathogenic variants/likely pathogenic variants (PV/LPV) with breast cancer and the role of risk-reducing mastectomy remain underexplored, especially in Asian populations." (PMID 41701219, 2025). "Therefore, HER2 positivity is relatively rare in breast cancer patients with BRCA1/2 germline mutations and is likely even less common in CRC." (PMID 39985003, 2025). "Despite significant progress, a substantial gap persists in our present comprehension of the association between adiposity and breast cancer biology in individuals with mutations in the BRCA1/2 genes, the most widely known high‐penetrance genes involved in severe breast cancer risk." (PMID 40523654, 2025). "Importantly, research conducted by CIMBA recognizing some of these variants as modifiers of breast cancer risk in carriers of BRCA1 and BRCA2 pathogenic variants." (PMID 40296163, 2025). "Breast cancer patients harboring mutations in BRCA1/2 genes are known to have the worst outcomes." (PMID 40565165, 2025). "However, such a ruthenium compound caused a reduction in BRCA1 expression in the tested breast cancer cells." (PMID 41155174, 2025). "We investigated whether germline BRCA1/2 pathogenic variants (PVs) influence treatment response and survival outcomes in breast cancer patients treated with neoadjuvant chemotherapy (NCT)." (PMID 40405286, 2025). "Additionally, this study aims to explore the potential impact of OPG on breast cancer risk in individuals carrying BRCA1/2 mutations, to elucidate the underlying mechanisms contributing to breast tumorigenesis and progression." (PMID 39941709, 2025). "Notably, around 60% of breast cancers linked to BRCA1 mutations present as triple-negative breast cancer." (PMID 41354912, 2025). "Furthermore, BRCA2 mutation/deletion is far more common in prostate cancer than BRCA1 loss of function, whereas in breast cancer, the relative frequencies on BRCA1 versus BRCA2 mutation are nearly equal." (PMID 40460119, 2025). "Although this study lacked power to detect risk increases larger than twofold, its findings are largely consistent with prior reports, suggesting that most established breast cancer risk factors do relatively little to modify breast cancer risk in BRCA1/2 PV carriers." (PMID 40298171, 2025). "Genetic Studies conducted among women with breast cancer in countries such as Ghana, Nigeria, Uganda, Cameroon, and South Africa have found that most breast cancer cases are associated with mutations of the tumor-suppressing genes - BRCA1 and BRCA2." (PMID 40313245, 2025). "However, the loss of RNF168 in BRCA1/2-mutated breast cancer cells has also been reported to lead to R-loop accumulation, which triggers double-strand breaks, senescence, and eventual cell death." (PMID 39996778, 2025). "Recent research suggests that lincRNAs may serve as valuable prognostic indicators, particularly for breast cancer patients with BRCA1 mutations." (PMID 39997609, 2025). "Overall, BRCA1/2 mutations are responsible for approximately 5% of breast cancer cases." (PMID 40142593, 2025). "Notably, the breast cancer susceptibility gene BRCA1 inhibits ERα acetylation by blocking p300 binding to ERα acetylation sites and/or by mono-ubiquitinating ERα at K302." (PMID 40641933, 2025). "The broader definition of hereditary tumors in our study, which included carriers of P/LP variants in breast cancer risk genes beyond the BRCA1/2 genes, may partly account for the larger number of DEGs observed." (PMID 41463479, 2025).
breast cancer (continued). "Of the 99 women with P/LP variants in BRCA1/2, 44 (44.4%) had personal history of breast cancer with the mean age at diagnosis being 40.2 years (range: 24–70), and 4 (4.1%) had personal history of ovarian cancer with the mean age at diagnosis being 36.3 years (range: 23–42)." (PMID 40445415, 2025). "Notably, one recent preclinical study in mice showed that depleting LIG3 renders BRCA1-deficient mammary tumors sensitive to poly (ADP-ribose) polymerase (PARP) inhibitors." (PMID 40768895, 2025). "The two BRCA1 variants should be included in a potential national carrier screening program for breast and ovarian cancer, as early detection of breast cancer may lead to decreased morbidity with improved cancer outcomes." (PMID 40699671, 2025). "Talazoparib, initially approved as a monotherapy in BRCA1/2-mutated breast cancer and in combination with enzalutamide for HR-deficient prostate cancer, is currently under Phase II investigation for patients with solid tumors harboring DDR gene mutations, including BARD1." (PMID 41009605, 2025). "This discrepancy may be attributed to the composition of our study population, which consisted primarily of patients with a personal history of breast cancer or a strong family history of HBOC who were confirmed as carrying a BRCA1/2 pathogenic variant." (PMID 40862027, 2025). "Moreover, BRCA1-mutated breast cancers have been shown to be more immunogenic than HR-proficient cancers." (PMID 41155174, 2025). "The role of germline copy number variants (CNVs) as breast cancer risk modifiers in women carrying BRCA1 and BRCA2 P/LP variants remains relatively unknown." (PMID 39858629, 2025). "The translational alignment of our preclinical findings with existing and emerging clinical paradigms positions the Brca1co/coMMTV-Cre mouse as an optimal platform for accelerated evaluation of next‐generation combination therapies targeting BRCA1‐deficient breast cancer." (PMID 41208884, 2025). "Approximately 75–80% of BRCA1 mutation-associated breast cancers are TNBC and basal-like." (PMID 40573960, 2025). "For GDM patients carrying breast cancer genetic susceptibility genes (such as germline mutations in BRCA1/2), hyperinsulinemia, and chronic inflammation may further impair the DNA damage repair capacity through the PI3K/Akt pathway." (PMID 40678319, 2025). "The reduced breast cancer-specific mortality in BRCA1/2 PV carriers could be linked to their tumors’ better response to chemotherapy and potentially more rigorous treatment regimens, including escalated chemotherapy protocols." (PMID 40405286, 2025). "Breast cancer patients with a BRCA1 mutation are also frequently triple-negative and basal-like." (PMID 41155174, 2025). "The overall prevalence of the studied BRCA1/2 variants in the unselected breast cancer cohort was 0.9% (21/2338, of which 7 BRCA1 and 14 BRCA2), which was significantly higher compared to controls (odds ratio [OR] 6.7, 95% confidence interval [CI] 2.24–19.70, p < 0.001)." (PMID 40009290, 2025). "As is well-established, BRCA1 mutations increase breast cancer risk in women." (PMID 41589155, 2025). "Therefore, breast cancer patients with BRCA1 somatic mutations are more likely to respond to the platinum drug carboplatin." (PMID 41155174, 2025).
breast cancer (continued). "The identification of germline BRCA1/2 (BRCA) mutations plays an important role in the treatment planning of high-risk breast cancer patients, but genetic testing may be costly or unavailable." (PMID 40942929, 2025). "It has also been suggested that BRCA1 may be associated with EC; however, this may be due to its strong association with breast cancer and hence tamoxifen use." (PMID 39901248, 2025). "To further explore whether mammary tumor growth with Brca1 deficiency could be affected by ERα, we performed allograft experiments." (PMID 40157910, 2025). "However, the specific risk for breast cancer development in BRCA1 mutation carriers, mistakenly suggested an underlying excess of estrogen signaling." (PMID 41514592, 2025). "Additionally, approximately 10% of women diagnosed with breast cancer before the age of 40 carry a BRCA1 or BRCA2 mutation." (PMID 41002733, 2025). "Before the development of breast cancer, PD-1+ immune cells in carriers with BRCA1 and BRCA2 germline mutations are preferentially localized near the epithelial tissue, which might be associated with early immune evasion in the malignant epithelial tissue." (PMID 40830526, 2025). "Efficacy was also tested in two independent BRCA1 mutated breast cancer PDX models." (PMID 39819384, 2025). "In addition, physical activity is associated with a significantly delayed onset of BC among breast cancer gene 1 and breast cancer gene 2 (BRCA1/2) mutation carriers." (PMID 40472337, 2025). "In breast cancer patients, the development of agranulocytosis and febrile neutropenia after the first chemotherapy cycle has even been shown to be an independent predictive factor for the detection of a BRCA1 germline mutation." (PMID 40519304, 2025). "Eligibility for BRCA1/2 genetic testing is currently determined on the basis of risk rather than symptoms: referrals are most commonly made on the basis of personal or family histories of breast cancer." (PMID 39812114, 2025). "Accordingly, we focused on the relationship between breast cancer arising from BRCA1 loss and increased tumor mutational burden, with the aim of assessing its potential as a predictive indicator for improved outcomes with immune checkpoint inhibitor (ICI) therapy." (PMID 41208884, 2025). "Consistent with prior studies, a sample was classified as HRD for training purposes (i.e., ground truth) if it had an HRD score of at least 42 for breast cancer or 63 for ovarian cancer or if it harbored pathogenic germline variants, somatic mutations, or promoter methylation in BRCA1 or BRCA2." (PMID 40327608, 2025). "To illustrate the new method, we selected the most significant 176 genes that could discriminate breast cancers with BRCA1 mutation from those with BRCA2 mutation, resulting in a 15×176 matrix." (PMID 41542084, 2025). "Sequencing of 5’UTR of BRCA1 gene in pre-selected breast cancer patients revealed a common variant BRCA1 c.20 + 101 C > G (rs799905) located within a CpG site, of which the G allele potentially might create a methylation site." (PMID 40495194, 2025). "A study published in The New England Journal of Medicine in 2019 reported that among patients with BRCA1/2-mutated advanced breast cancer who received talazoparib, an FDA-approved PARP inhibitor, the objective response rate was 62.6% and the median progression-free survival was 8.6 months." (PMID 39844055, 2025). "Additionally, patients with BRCA1/2 germline pathogenic variants have a risk of developing contralateral breast cancer (CBC)." (PMID 40626017, 2025). "In addition, a higher risk of developing diabetes after the diagnosis of breast cancer for BRCA1/2 mutation carriers has been described." (PMID 39621070, 2025). "Additionally, TNBC is more common in individuals with a family history of breast cancer, particularly those carrying deleterious germline mutations in genes like BRCA1." (PMID 41249701, 2025).
breast cancer (continued). "Our findings suggest that, while some variability exists, BRCA1-breast cancer risk may be less strongly influenced by specific PV than previously thought." (PMID 41440233, 2025). "Additionally, the BRCA-1 gene mutation, which is crucial in breast cancer, affects the regulation of VEGF, which leads to the dysregulation of the gene and increases angiogenesis in humans." (PMID 40724530, 2025). "Furthermore, we found that depletion of either TLK1 or TLK2 in breast cancer and ovarian cancer cells with BRCA1 deficiency leads to increased resistance to PARPi." (PMID 39844055, 2025). "Conversely, ZNF251 haploinsufficiency in BRCA1-mutated breast cancer may reduce PARPi sensitivity by restoring HR function." (PMID 40864792, 2025). "However, in the Beitsch study, it was shown that if genetic tests were performed only based on the NCCN Criteria, and when only the BRCA1/2 or limited panels were tested, about 45% of breast cancer patients with germline variants would be ignored." (PMID 41541272, 2025). "(“fertility preservation” OR “oocyte cryopreservation” OR “embryo cryopreservation”) AND (“BRCA mutation” OR “BRCA1” OR “BRCA2”) AND (“hormone receptor status” OR “ER positive” OR “PR positive” OR “triple-negative breast cancer” OR “TNBC”) AND (“breast cancer”)." (PMID 41395617, 2025). "Premenopausal salpingo-oophorectomy, recommended for BRCA1/2 PV carriers given their high ovarian cancer risk, has been variably associated with lower breast cancer risk (in range of 0.2–0.9) depending on the affected gene and age at surgery and aligns with general population findings." (PMID 40298171, 2025). "While lincRNAs have been implicated in several cancer types, including BRCA1-mutated breast cancer, their therapeutic significance in breast cancer remains unclear." (PMID 39997609, 2025). "Insights into the cross‐talk between obesity and breast cancer development in BRCA mutation carriers may pave the way to improve proper personalized clinical management of BRCA1/2‐associated breast cancer." (PMID 40523654, 2025). "Additionally, germline mutations in the tumour suppressor genes breast cancer susceptibility genes 1 and 2 (BRCA1 and BRCA2) increase the risk of breast, ovarian, and related cancers." (PMID 40429877, 2025). "Although pamiparib previously demonstrated antitumor activity in cell lines with breast cancer genes 1/2 (BRCA1/2) mutations or other homologous recombination deficiencies, its effect on homologous recombination deficiency was not assessed in the current study." (PMID 41149461, 2025). "Additionally, genetic mutations, such as those in BRCA1, influence the risk of breast cancer development in relation to OPG expression." (PMID 39941709, 2025). "Indeed, patients carrying BRCA1 mutations have a lifetime risk of breast cancer of 40%–87%, while the risk in those with BRCA2 mutations is 25%–30%." (PMID 40338860, 2025). "A study in Spain found that the carrier frequency of the 185delAG BRCA1 mutation in Romani individuals could be several times higher than in the general population, putting them at a greater risk of breast cancer." (PMID 39963159, 2025). "Importantly, in all cases, induction of SCEs was markedly higher compared to BRCA1-mutated breast cancer cell lines, used as positive controls." (PMID 40721661, 2025). "In addition, we aimed to estimate the risk of breast cancer and overall mortality in BRCA1/2 carriers according to BRRM and RR-BSO status and compared to a matched control group." (PMID 40974500, 2025). "A literature review indicates that BRCA1 deficiency may impair bone marrow recovery after chemotherapy, as observed in breast cancer patients, which we hypothesize also applies in this case." (PMID 40519304, 2025).